BCL2 (BCL2 apoptosis regulator)
Diseases named in the same sentence as BCL2 in open-access papers (continued):
Sharing a sentence is not in itself a finding about the gene and the disease.
cancer (continued). "Many cancer cells develop a mechanism to foreclose programmed cell death through the overproduction of proteins that prevent apoptosis, e.g., Bcl-2 and Bcl-XL." (PMID 35340213, 2022). "A limitation of the current study is the use of mouse cells expressing Bcl-2; thus, it would be of great value to examine this effect in human cancer cells." (PMID 36539401, 2022). "The antiapoptotic Bcl-2 proteins are frequently overexpressed in cancer and prevent apoptosis by blocking the activity of the proapoptotic Bcl-2 family members." (PMID 34374809, 2022). "It has been revealed that in cancer cells, cardiac glycosides induce apoptosis by down-regulating the anti-apoptotic proteins Bcl-XL and Bcl-2 as well as Mcl-1 and increasing the pro-apoptotic proteins Bid and Bax57,58,86–89." (PMID 35778548, 2022). "Treatment with 7b mainly reduced BCL2 activity, thus induces apoptosis, and limits cancer progression." (PMID 35164019, 2022). "The Cell cycle-regulating genes are inactivated in cancer cells, and Bcl-2) adjusts their expression in tumors." (PMID 36034846, 2022). "Predictably, Bcl-2 as well as other anti-apoptotic Bcl-2 family members have been found to be overexpressed in a variety of human cancers." (PMID 36539401, 2022). "It is also interesting to note that the evolution of placental invasion and cancer metastasis appears to be causally linked, sharing as reported IGF/MAPK, BCL2, Wnt-signalling and, most importantly, immune evasion." (PMID 36499258, 2022). "PKC in chronic Cr(VI)-treated cells stabilizes Bcl-2 to mitigate doxorubicin (an anti-cancer drug)-mediated apoptosis." (PMID 35210368, 2022). "When the global cap-dependent translation was rapidly inhibited, cancer cells would replenish the BCL-2 level by IRES to adapt to cell apoptosis stress." (PMID 36365147, 2022). "Silver nanoparticles combined with berberine enhanced the expression of Bcl-2, whereas the ratio of Bax/Bcl-2 decreased in cancer cells." (PMID 36144625, 2022). "The anti-apoptotic proteins BCL-2, BCL-xL and MCL-1 prevent MOMP through directly interacting with the pro-apoptotic proteins, protecting cancer cells from stress stimuli caused by chemotherapies." (PMID 36013602, 2022). "For example, when BCL-2 is highly expressed in the body, cancer cells will resist drugs or chemotherapy during treatment, reducing the therapeutic effect of cancer." (PMID 36313628, 2022). "Bcl-2 inhibits programmed cell death in cancers and promotes cell survival, supporting cancer resistance to drugs." (PMID 36559264, 2022). "From the KEGG software was chosen the pathway in cancer, in which Bcl2 and CDK6 are target genes related to the activity of EDCs." (PMID 36498866, 2022). "One of the possible strategies to overcome the cancer cell resistance towards Bcl-2 or Mcl-1 inhibitors is to use combination of both inhibitors." (PMID 36267274, 2022). "Since BCL-2 proteins potentially block apoptosis via the intrinsic pathway and are found at elevated levels in cancers, especially blood cancers, they are promising targets for therapeutic interventions." (PMID 36500355, 2022). "Bcl-2 plays an important role in cell apoptosis induced by anticancer agents; Bcl-2 overexpression was reported in many cancers." (PMID 36363906, 2022).
cancer (continued). "BCL2 has an immunoglobulin-specific sequence (NMD-escape mutation) in its 3′ UTR; this prevents its NMD-mediated mRNA degradation, resulting in a high level of BCL2 in cancer." (PMID 36552825, 2022). "Still, there is scope to determine its role in other important cancer-related pathways like modulation of Bax-Bcl-2 cascade." (PMID 35402265, 2022). "Bcl2 is critical for cell death processes and is proposed as a promising target for human gene therapy in cancers." (PMID 35013138, 2022). "In another cancer biosensor report, an immunosensor was developed for the direct recognition of Bcl-2 and Bax in cancer cell cultures." (PMID 36236638, 2022). "An unbalanced state betweenpro- versus anti-apoptotic BCL-2 proteins can act as a barrier to apoptosis and facilitate cancer development." (PMID 36518133, 2022). "Activation of proapoptotic signaling pathways is an important goal in cancer therapy, which is often blocked by antiapoptotic Bcl-2 proteins." (PMID 36293331, 2022). "In this study, Bcl-2 and Bcl-xl, which are generally highly expressed in cancer cells, were detected for their anti-apoptotic properties." (PMID 35645820, 2022). "Its modulation by anti-apoptotic protein B-cell lymphoma 2 (Bcl-2) plays an important role in cancer progression." (PMID 36045908, 2022). "Several cancer therapy strategies have focused on sensitizing cells to mitochondrial apoptosis, for instance, via Bcl-2 inhibitors." (PMID 35454774, 2022). "In three cancer cell lines, mRNA levels of Bcl2, APAF1, and caspase-3 were evaluated at ascending concentrations and around IC50 concentrations by real-time-qPCR reported by fold change." (PMID 36204226, 2022). "Many anti-cancer mechanisms are related to apoptosis, including the caspase pathways and Bax/BCL2 proteins." (PMID 36009221, 2022). "The bacteria can also prevent cancer by downregulating the nuclear factor-kappaB-dependent gene products, which regulate cell proliferation (Cox-2, cyclin D1) and survival (Bcl-2, Bcl-xL)." (PMID 35993063, 2022). "VTX acts as a selective inhibitor of the BH3 domain of Bcl-2 that can restore apoptosis in cancer cells." (PMID 35682939, 2022). "The viable anti-cancer strategies are based on developing anti-apoptotic Bcl-2 proteins inhibitors, BH3 mimetics." (PMID 36267274, 2022). "Bcl-2 antagonist ABT-737 slights the apoptotic threshold to chemotherapeutic drugs via the PI3K/Akt signaling inhibition in cancer cells." (PMID 35402265, 2022). "The three derivatives activated caspase up to 4.2 folds in the treated cancer cells, downregulated Bcl2 and induced apoptosis (up to 58.7%)." (PMID 36575196, 2022). "Significantly, elevated expression of BCL-2 has been detected in more than half of all cancer cases." (PMID 36230771, 2022). "Research has demonstrated that necroptosis is able to overcome resistance to cancer drugs mediated by P-glycoprotein, Bcl-2, and Bcl-xL in cancer cell lines." (PMID 36291937, 2022). "CPE promotes the survival of cancer cells by upregulating the expression of anti-apoptotic protein Bcl-2 and other pro-survival genes via the ERK1/2 pathway activation." (PMID 35686102, 2022). "It was also reported that the augmented level of Bcl-2 phosphorylation correlated well with the increase of the resistance of small cell lung cancer cells to anti-cancer drugs." (PMID 35210368, 2022). "As a proof‐of‐concept study, antisense sequence (G3139) that targets BCL‐2 gene, a key regulatory gene to inhibit apoptosis of cancer cells, was selected and two PS modifications were introduced to the ASO sequence for drug grafting." (PMID 37323880, 2022).
cancer (continued). "It is of interest to document the molecular docking analysis data of lupeol with different cancer targets such as Caspase- 3, BCL-2, Topoisomerase, PTK, mTOR, H-Ras, PI3K, AKT." (PMID 36518133, 2022). "It has been well documented that chemoresistance is induced by the inhibition of pro-apoptotic proteins such as PTEN, BAX and Bad and the overexpression of anti-apoptotic proteins such as p-AKT, survivin, XIAP, Bcl-2 and Bcl-xL in resistant cancer cells." (PMID 35456022, 2022). "Oridonin exerts its anti-cancer activity by inducing mitochondria-mediated apoptosis through augmentation of Bax/Bcl-2 ratio, and activation of caspase–3 and 9, accompanied by augmented reactive oxygen species (ROS) production." (PMID 35956961, 2022). "In this study, Agr was found to increase ROS generation, block Bcl-2 expression, and increase Caspase-3 and Bax expression to promote cancer cell apoptosis." (PMID 36591497, 2022). "Numerous reports have also suggested that the transcription factors nuclear factor‐kB (NF‐kB) and activator protein‐1 (AP‐1) can regulate the expression of Bcl‐2 leading to the transition of benign carcinomas towards malignant phenotype." (PMID 35611809, 2022). "SMG-induced apoptosis with a reduction in Bcl-2 has been reported in endothelial cells, osteoblastic cells, and carcinoma cells." (PMID 36591304, 2022). "BCL-2 regulation shows inconsistency with previous research due to the adaptive regulation (abnormal BCL-2 expression) of carcinoma cells in low levels of PTX." (PMID 35509628, 2022). "In fact, Bcl-2 was reported to be overexpressed in intestinal adenomas, precluding carcinogenesis and their transformation into carcinomas in mice and human beings." (PMID 35448666, 2022). "Given that the increased expression levels of Bcl-2, Bcl-xL, and Mcl-1 are frequently observed in tumor tissues, these proteins constitute important therapeutic targets for cancer therapy." (PMID 33418995, 2021). "Along this line, BH3 mimetics, inhibiting anti-apoptotic BCL2 proteins, are confirmed to be sufficient to prime cancer cells to various chemotherapeutics, including paclitaxel." (PMID 34903710, 2021). "The anti-apoptotic Bcl-2 proteins have also gained increasing importance for therapeutic targeting, from their abilities to drive cancer progression and the most extensive studies of which have described the targeting of Bcl-2, Bcl-xL, and Mcl-1." (PMID 33925117, 2021). "CGA was also found to induce apoptosis by upregulating the expression of both pro-apoptotic Bax and caspase-3 proteins and downregulating the level of the anti-apoptotic Bcl-2 protein in kidney (A-498) and lung (A549) cancer cells." (PMID 34641577, 2021). "As such, combination strategies utilising BH3-mimetics with other anti-cancer agents that indirectly modulate the pro-survival function of BCL-2 proteins, are being investigated in solid cancers as an alternate and safer approach." (PMID 34581776, 2021). "Disarib was proven to inhibit the growth of Bcl-2 high cancer cell lines and CLL patient primary cell lines with minimum effect on Bcl-2 low cancer cell lines." (PMID 33535550, 2021). "We investigated the sensitivity of densities of cancer cells (C), IL-6 (L), NF-κB (F), Bcl-2 (B) and BAX (X) to these parameters at several time points." (PMID 34669701, 2021). "Myeloid cell leukemia 1 (MCL1) is an important antiapoptotic member of the BCL2 gene family that is frequently overexpressed in several human cancer types, including CML." (PMID 34564697, 2021). "In Caco2 and HeLa cancer cells, orthorhombic tungsten oxide NPs decreased cell viability by 65% and 73%, respectively, by reducing the expression of Bcl-2 and MMP7." (PMID 33923200, 2021). "IL-11 induces Signal transducer and activator of transcription 3 (STAT3) phosphorylation and increases the expression of anti-apoptotic protein Bcl-2 and Survivin in cancer cells." (PMID 34503172, 2021).
cancer (continued). "It has been observed for many years, in many studies, that ALK+ ALCL has characteristically low expression levels of B-cell Lymphoma 2 (BCL2) proteins, whereas BCL2 overexpression is a classical feature of cancers, including hematopoietic tumors." (PMID 34685497, 2021). "The results achieved with mouse models are similar to the detected impact of the expression of Bcl-2 in cancers." (PMID 34638779, 2021). "Further analyses showed that LACBio1, LACBio2, LACBio3 and LACBio4 exert cytotoxic effects on MDA-MB 231 cancer cell line by inducing the intrinsic apoptosis pathway, activating caspase 9 and Bax/Bcl-2 pathway in vitro." (PMID 34361566, 2021). "Lactobacillus acidophilus and L. delbrueckii bacterial supernatants revealed their anticancer property on AGS MCS-7 SW620 and HT-29 cancer cell lines by the induction of the caspase-3-dependent apoptosis pathway and reduction of Bcl2 expression." (PMID 33506004, 2021). "More importantly, anti-apoptotic Bcl-2 proteins are widely over-expressed in cancers and have been established to contribute to therapy resistance, recurrence and poor prognosis." (PMID 34118966, 2021). "They found that endothelial cells overexpressing Bcl-2 (EC-Bcl-2) can display a higher affinity for cancer cells via overexpressed E-selectin and can decrease the apoptosis of CTCs." (PMID 34834295, 2021). "Bcl-2, a highly conserved anti-apoptotic protein plays a central role in acquiring resistance to cancer therapy." (PMID 34921322, 2021). "The anti-apoptotic proteins of the Bcl-2 family, such as Bcl-2 and Bcl-XL, prevent proapoptotic proteins that are needed to initiate mitochondrial apoptosis, which eventually leads to cancer cell survival." (PMID 34667663, 2021). "Further studies reported that gene amplification, augmented expression, translation, and protein stability were responsible for higher antiapoptotic Bcl-2 in cancers." (PMID 34830349, 2021). "Consistently, cell studies on BC cells demonstrated upregulated apoptosis in BCL2-positive human cancer cells after the activation of RXR." (PMID 34359656, 2021). "It seems that SPNs, through increase in miR-34a expression, suppress Bcl2 and cancer stem cell surface markers." (PMID 34094034, 2021). "Activation of Bcl-2 is also involved in protective autophagy in cancer stem cells via EGFR signaling." (PMID 34829834, 2021). "Till date, cell cycle arrest and apoptosis have been reported as the primary mode of action of Artemisinin and its derivatives in cancer cells with Bax, Bcl2, caspase 3, cyclinB1, Cdc2 and Mdm2 as its popularly recognized targets." (PMID 34900697, 2021). "Given that apoptosis inhibition is an important feature of cancer, we measured levels of the antiapoptotic protein Bcl-2 and of the proapoptotic proteins Bax and caspase-3 to further explore the role of COMP in apoptosis of PTC cells." (PMID 33613749, 2021). "The findings revealed that icariin promoted cancer cell apoptosis by regulating the expression of Bcl-2/Bax and cytochrome c, activation of caspase-9, and -3." (PMID 33920726, 2021). "This reason supported that the potential BmKn-2 action inhibited cancer cell proliferation and induced apoptosis via Bcl-2 down-regulation and Bax up-regulation gene expressions." (PMID 34359246, 2021). "The apoptosis-related proteins, such as Bcl-2, Bax, and caspase-3, regulate cancer cell apoptosis or survival, which was confirmed to be related to many cancers and diseases." (PMID 33430124, 2021).
cancer (continued). "Previous reports have demonstrated that cancer cells harboring aberrant STAT3 activities elevate levels of anti-apoptotic proteins such as BCL2, BCL-xL, and myeloid cell leukemia 1 (MCL1)." (PMID 34268250, 2021). "Caspase-3, Caspase-8, Bax and Bcl-2 levels for hybrid 4b and staurosporine on HepG2 cancer cell line." (PMID 34832959, 2021). "Recently, the sustained high expression of Survivin and Bcl-2 is shown to protect cancer cells from drug-induced apoptosis, thereby driving MDR." (PMID 33738259, 2021). "After the cells were treated with compound 5c, Bcl-2, Bax, and FasL levels in all cancer cell lines were greater than those of the control group." (PMID 34249261, 2021). "This pathway, however, is controlled by antiapoptotic Bcl-2 proteins, among them Mcl-1, which is a key regulator of antiapoptotic, prosurvival signaling in cancer cells." (PMID 34028599, 2021). "Since the BCL-2 proteins are key regulators of the maintenance of ER–mitochondria homeostasis to encourage evasion of cancer cell apoptosis." (PMID 34064109, 2021). "The proto-oncogene bcl-2 appears to serve a critical antiapoptotic function, both in developing cancer and creating drug resistance." (PMID 35054564, 2021). "Lut can attenuate antitumor activity and drug resistance via reducing Bcl-2 expression in cancer cells." (PMID 34722681, 2021). "Bcl-2 plays a central role in the regulation of apoptosis that is a major contributor to cancer development." (PMID 34638779, 2021). "Several studies have confirmed that BCL-2 offers potential as a prospective drug target, as it activates the proto-oncogenic effect of the cancer environment." (PMID 35009072, 2021). "For example, disequilibrium between pro- and anti-apoptotic BCL2 proteins can promote cancer cell survival." (PMID 34046198, 2021). "Linalool has been shown to lead to a reduction in BCL-2 protein expression in human dermal fibroblast cancer cell lines." (PMID 35009072, 2021). "Human cancer cells are commonly resistant to apoptosis due to the overexpression of anti-apoptotic Bcl-2 family (e.g. Bcl-2, Mcl-1 and Bcl-xL) or alternatively, due to down-regulation of pro-apoptotic BH3-only proteins (e.g. Noxa, Bik or Puma)." (PMID 33691728, 2021). "The anti-apoptotic BCL2 was higher than the control, which is quite expected in most cancer cell lines, but had a decreasing trend in the treated groups." (PMID 33869169, 2021). "Upregulation of the expression of pro-apoptotic proteins such as Bax and downregulation of anti-apoptotic proteins such as Bcl-2 can prevent apoptosis of cancer cells." (PMID 33953676, 2021). "The membrane location of Bcl-2 and its conformational state seems to be important for its cell-protecting activity, often infamously upregulated in cancers." (PMID 33907308, 2021). "Bcl-2 is a protein that is overexpressed in benign and malignant neoplasms; the overexpression of Bcl-2 positively modulates proteins such as IAP-2, inhibiting apoptosis." (PMID 34987583, 2021). "MiRNA MIR497 with low expression silenced target genes BECN1, MTDH, and BCL2 to indulge cancer cell differentiation, angiogenesis, and metastasis." (PMID 33802957, 2021).